OR6N1 (olfactory receptor family 6 subfamily N member 1)
Description:
Odorant receptor.
Synonyms: OR1-22
Tractability: Antibody: UniProt places it where antibodies can reach, with medium confidence; UniProt predicts a signal peptide or a membrane-spanning region; its Gene Ontology location is reachable by antibodies, with medium confidence.
Gene: Protein-coding gene on chromosome 1 (158,747,814 to 158,772,195, reverse strand). Ensembl gene ENSG00000197403.
Subcellular location: Cell membrane
Pathways (Reactome):
Sensory Perception: Expression and translocation of olfactory receptors
Gene Ontology:
Molecular function: olfactory receptor activity; G protein-coupled receptor activity
Biological process: detection of chemical stimulus involved in sensory perception of smell; G protein-coupled receptor signaling pathway
Cellular component: plasma membrane; membrane
Genetic constraint (gnomAD): Missense variants: 374 observed, 368.22 expected, observed/expected ratio (o/e) 1.02, 90% interval 0.93 to 1.11. Synonymous variants: 160 observed, 150.13 expected, observed/expected ratio (o/e) 1.07, 90% interval 0.94 to 1.22.
Homologues: Orthologues: chimpanzee OR6N1 (98% identical), macaque OR6N1 (95% identical), rabbit OR6N1 (91% identical), mouse Or6n1 (88% identical), rat Or6n1 (88% identical), dog OR6N1 (87% identical). Paralogues in human: OR6N2 (66% identical), OR6K3 (53% identical), OR6K2 (52% identical), OR6K6 (50% identical), OR1L1 (46% identical), OR1L4 (46% identical), OR10Z1 (45% identical), OR1L6 (45% identical), OR7C1 (45% identical), OR1F1 (45% identical), OR1L3 (44% identical), OR7C2 (44% identical), and 116 more.
Diseases named in the same sentence as OR6N1 in open-access papers:
OR6N1 is named in the same sentence as 2 diseases in open-access papers, as found by Europe PMC text mining. Sharing a sentence is not in itself a finding about the gene and the disease.
OR6N1 shares sentences with these, for which no sentence is quoted: cancer (1 paper); entropion (1).